MIR3661 (microRNA 3661)
Synonyms: hsa-mir-3661; mir-3661
Gene: MicroRNA gene on chromosome 5 (134,225,757 to 134,225,852, forward strand). Ensembl gene ENSG00000266751.
Homologues: Orthologues: chimpanzee MIR3661 (100% identical), macaque MIR3661 (100% identical), rabbit MIR3661 (100% identical).